SLC9A1 (solute carrier family 9 member A1)
Description:
Electroneutral Na(+) /H(+) antiporter that extrudes Na(+) in exchange for external protons driven by the inward sodium ion chemical gradient, protecting cells from acidification that occurs from metabolism. Exchanges intracellular H(+) ions for extracellular Na(+) in 1:1 stoichiometry (By similarity). Plays a key role in maintening intracellular pH neutral and cell volume, and thus is important for cell growth, proliferation, migration and survival. In addition, can transport lithium Li(+) and also functions as a Na(+)/Li(+) antiporter. SLC9A1 also functions in membrane anchoring and organization of scaffolding complexes that coordinate signaling inputs.
Synonyms: NHE-1; NHE1; PPP1R143; APNH; LIKNS
Tractability: Small molecule: a structure with a bound ligand is known; a high-quality ligand is known; it belongs to a druggable protein family. Antibody: UniProt places it where antibodies can reach, with high confidence; its Gene Ontology location is reachable by antibodies, with high confidence; UniProt predicts a signal peptide or a membrane-spanning region; the Human Protein Atlas places it where antibodies can reach. PROTAC: it is named in the literature on targeted protein degradation; UniProt records ubiquitination sites on it; ubiquitination databases record sites on it; its protein half-life has been measured; a small molecule that binds it is known.
Target class: SLC superfamily of solute carriers; SLC09 family of sodium/hydrogen exchangers; Electrochemical transporter; Transporter
Chemical probes: BI-9627 (high quality), d9A-2 (high quality)
Gene: Protein-coding gene on chromosome 1 (27,098,809 to 27,166,981, reverse strand). Ensembl gene ENSG00000090020.
Subcellular location: Cell membrane; Basolateral cell membrane
Subcellular location (Human Protein Atlas): Plasma membrane; Nucleoplasm
Pathways (Reactome):
Metabolism: Hyaluronan degradation
Transport of small molecules: Sodium/Proton exchangers
Gene Ontology:
Molecular function: calcium ion binding; calcium-dependent protein binding; identical protein binding; phospholipid binding; protein binding; protein phosphatase 2B binding; sodium:proton antiporter activity; molecular adaptor activity; phosphatidylinositol-4,5-bisphosphate binding; protein-macromolecule adaptor activity; antiporter activity
Biological process: cellular response to acidic pH; cellular response to epinephrine stimulus; hyaluronan catabolic process; intracellular sodium ion homeostasis; positive regulation of calcineurin-NFAT signaling cascade; positive regulation of cardiac muscle hypertrophy; positive regulation of the force of heart contraction; positive regulation of transcription by RNA polymerase II; proton transmembrane transport; regulation of cardiac muscle contraction by calcium ion signaling; regulation of intracellular pH; regulation of pH; regulation of the force of heart contraction by cardiac conduction; response to acidic pH; response to muscle stretch; sodium ion import across plasma membrane; cell migration; cellular response to mechanical stimulus; maintenance of cell polarity; protein complex oligomerization; regulation of cardiac muscle cell membrane potential; regulation of focal adhesion assembly; regulation of stress fiber assembly; sodium ion export across plasma membrane; sodium ion transmembrane transport; and 17 more
Cellular component: cation-transporting ATPase complex; cytoplasm; extracellular exosome; focal adhesion; membrane raft; plasma membrane; basolateral plasma membrane; lamellipodium; membrane; apical plasma membrane; cell surface; intercalated disc; perinuclear region of cytoplasm; sarcolemma; T-tubule; transporter complex
Genetic constraint (gnomAD): Loss-of-function variants: 22 observed, 66.41 expected, observed/expected ratio (o/e) 0.33, 90% interval 0.24 to 0.47. The upper end of that interval is the gene's LOEUF score, 0.47, which puts it in group 2 of 6, group 1 being the genes least tolerant of losing a copy. Missense variants: 685 observed, 1,113.7 expected, observed/expected ratio (o/e) 0.62, 90% interval 0.58 to 0.65. Synonymous variants: 420 observed, 484.32 expected, observed/expected ratio (o/e) 0.87, 90% interval 0.8 to 0.94.
Gene-disease validity (ClinGen):
ClinGen rates the evidence that SLC9A1 causes each of these diseases.
Lichtenstein-Knorr syndrome (autosomal recessive): Moderate. An autosomal recessive spinocerebellar ataxia caused by disease-causing variants in the SLC9A1 gene, characterized by early-onset cerebellar ataxia, cognitive or developmental delay, seizure, and cerebellar atrophy.
Homologues: Orthologues: chimpanzee SLC9A1 (99% identical), macaque SLC9A1 (99% identical), pig SLC9A1 (96% identical), dog SLC9A1 (96% identical), rabbit SLC9A1 (95% identical), rat Slc9a1 (93% identical), guinea pig SLC9A1 (93% identical), mouse Slc9a1 (93% identical), tropical clawed frog slc9a1 (75% identical), zebrafish SLC9A1 (53% identical), zebrafish slc9a1b (52% identical), Drosophila melanogaster Nhe2 (40% identical), and 5 more. Paralogues in human: SLC9A2 (44% identical), SLC9A4 (39% identical), SLC9A3 (35% identical), SLC9A5 (35% identical), SLC9A6 (19% identical), SLC9A7 (19% identical), SLC9A9 (19% identical), SLC9A8 (18% identical), SLC9C1 (16% identical), SLC9C2 (16% identical).
Diseases named in the same sentence as SLC9A1 in open-access papers:
SLC9A1 is named in the same sentence as 162 diseases in open-access papers, as found by Europe PMC text mining. Sharing a sentence is not in itself a finding about the gene and the disease. The quoted sentences say what the papers report.
breast carcinoma (87 papers, 2004 to 2025). "Through multi-omics analysis of GEO and TCGA cohorts, we identified two sodium homeostasis-related genes, TRPM4 and SLC9A1, as consistently upregulated oncogenes in breast cancer, with significant diagnostic and prognostic relevance." (PMID 41235237, 2025). "Accordingly, high SLC4A7 but low SLC9A1 mRNA expression is associated with poor survival in select breast cancer molecular subtypes." (PMID 34219652, 2021). "Although somatic mutations in TRPM4 and SLC9A1 are relatively rare events in breast cancer overall, the specific mutations that do occur may offer valuable functional insights." (PMID 41235237, 2025). "Mutations in TRPM4 and SLC9A1 were observed in 32 high-grade breast cancer tissues." (PMID 41235237, 2025). "This study elucidates the pathogenic roles of TRPM4 and SLC9A1 in breast cancer progression." (PMID 41235237, 2025). "The functional states of TRPM4 and SLC9A1 in breast cancer were investigated using the CancerSEA database." (PMID 41235237, 2025). "adMSC-Exos secreted miR-1236 enhanced the sensitivity of breast cancer cells to cisplatin (DDP) involving the downregulation of SLC9A1 downregulation and Wnt/β-catenin inactivation." (PMID 39308520, 2024). "Mechanistic investigation demonstrated that ADMSC-derived exosomes enhanced sensitivity to DDP by downregulating SLC9A1 via miR-1236 in breast cancer." (PMID 36100944, 2022). "The level of SLC9A1 mRNA, encoding NHE1, was most abundant in normal-like, luminal A, and HER2-enriched breast cancer, lower in luminal B breast cancer, and lowest in basal-like breast cancer." (PMID 34219652, 2021). "HER2-positive breast carcinomas have elevated protein expression of Na+/H+ exchanger NHE1/SLC9A1 and Na+,HCO3– cotransporter NBCn1/SLC4A7." (PMID 34219652, 2021). "As a proof of concept, we tested the activity of SLC9A1 (NHE1), a well-known Na+/H+ Exchanger known to be involved in breast cancer metastasis, especially in basal breast cancer subtypes." (PMID 34750607, 2021). "It is especially noticeable that the protein expression levels of NBCn1 and NHE1 are elevated in breast cancer tissue with HER2 overexpression or gene amplification despite low SLC4A7 and intermediate SLC9A1 mRNA levels." (PMID 34219652, 2021). "Protein expression of the Na+/H+ exchanger NHE1 (SLC9A1) is more variable in primary breast cancer tissue showing unchanged or only moderately elevated levels when compared to normal breast tissue as one unstratified group." (PMID 34219652, 2021). "The levels of SLC9A1 mRNA, encoding NHE1, vary among breast cancer subtypes, and high SLC9A1 expression is associated with improved survival in patients with luminal A breast cancer." (PMID 34219652, 2021). "(A) Variation in SLC9A1 mRNA levels among patients with different breast cancer subtypes (n=135–344)." (PMID 34219652, 2021). "Based on the negative relationship between NHE1 expression and lymph node metastasis and considering the improved survival of luminal A breast cancer patients with high SLC9A1 expression, we propose that NHE1 is a metastasis suppressor in human breast cancer." (PMID 34219652, 2021). "TRPM4 and SLC9A1 is a novel prognostic biomarker and potential therapeutic target in breast cancer." (PMID 41235237, 2025). "Adipose-derived MSC-exosomes could deliver miR-1236 to increase the sensitivity of breast cancer cells to DDP by participating in SLC9A1 downregulation and Wnt/β-catenin inactivation." (PMID 38294569, 2024). "Furthermore, overexpression of SLC9A1 reversed the inhibitory effects of ADMSC-derived exosomal miR-1236 on DDP resistance by activating the Wnt/β-Catenin signalling pathway in breast cancer." (PMID 36100944, 2022). "Therefore, the primary clinical relevance of TRPM4 and SLC9A1 in breast cancer is more robustly underscored by their frequent mRNA/protein overexpression and strong association with poor prognosis, as demonstrated throughout our study, rather than by their mutational status." (PMID 41235237, 2025).
breast carcinoma (continued). "MiR-1236, carried by AMSC-EVs, can promote the inhibition of breast cancer cell viability and apoptosis induced by DDP by suppressing SLC9A1 and the Wnt/β-Catenin signaling pathway." (PMID 38164177, 2024). "In breast cancer, AMSC-EVs can suppress the expression of SLC9A1 through miR-1236, resulting in the inhibition of the Wnt/β-catenin signaling pathway and thereby enhancing the sensitivity of breast cancer cells to DDP103." (PMID 38164177, 2024). "Net acid extrusion from breast cancer cells occurs mostly via the Na+, HCO3–-cotransporter NBCn1/SLC4A7 and Na+/H+-exchanger NHE1/SLC9A1." (PMID 37098526, 2023). "SLC9A1 has been shown to contribute to pHi regulation in cultured MCF-7 cells and human breast cancer slices." (PMID 24795638, 2014).
heart failure (40 papers, 2013 to 2025). Inability of the heart to pump blood at an adequate rate to meet tissue metabolic requirements. "Furthermore, SLC9A1 and CACNA1E have been reported to regulate the development of other heart diseases, such as heart failure and arrhythmia." (PMID 33407844, 2021).
glioma (34 papers, 2011 to 2025). A benign or malignant brain and spinal cord tumor that arises from glial cells (astrocytes, oligodendrocytes, ependymal cells). "In glioma, sodium/hydrogen exchanger 1 (NHE1), encoded by the SLC9A1 gene has been studied as a marker tumorigenesis and prognosis." (PMID 40548056, 2025). "In this study, we found that high SLC9A1 mRNA was associated with malignancy of gliomas and predicted a poor prognosis of glioma patients." (PMID 30333031, 2018). "Collectively, these data are consistent with our analysis of SLC9A1 expression of TCGA and CGGA dataset, suggesting that high levels of NHE1 protein expression are associated with malignant progression of gliomas." (PMID 30333031, 2018). "Sodium/hydrogen exchanger 1 (NHE1), encoded by the SLC9A1 gene (SoLute Carrier family 9A1) in humans, is the main H+ efflux mechanism in maintaining alkaline intracellular pH (pHi) and Warburg effects in glioma." (PMID 30333031, 2018). "Therefore, higher SLC9A1 mRNA expression is associated with the malignancy of gliomas." (PMID 30333031, 2018). "Studies have detected upregulated protein and mRNA (SLC9A1) expression of NHE1 in primary human glioma cells, glioma xenografts, and glioblastomas." (PMID 36768856, 2023). "In summary, this is the first study to delineate the molecular and clinical characteristics of SLC9A1 mRNA expression in gliomas." (PMID 30333031, 2018). "Analysis of SLC9A1 mRNA expression in two data sets, CGGA and TCGA, reveals significantly higher SLC9A1 mRNA levels in higher grade gliomas." (PMID 30333031, 2018). "We then performed the Kaplan-Meier analysis and Cox proportional hazard model to assess the prognostic values of SLC9A1 mRNA expression in gliomas." (PMID 30333031, 2018). "To further understand the biological roles of NHE1 expression in gliomas, we analyzed correlation between SLC9A1 mRNA and 1020 genes in the CGGA cohort or 1332 genes in the TCGA cohort by Pearson correlation analysis (with Pearson coefficient |R| > 0.4)." (PMID 30333031, 2018). "In both two databases, we found that SLC9A1 mRNA expression was higher in the IDH-wildtype than in the IDH-mutant gliomas." (PMID 30333031, 2018). "In this study, we further depicted the SLC9A1 mRNA expression pattern in different grade gliomas from CGGA and TCGA two independent databases." (PMID 30333031, 2018). "Meanwhile, we also found that the metagene score of CD8+ T cells and cytotoxic lymphocytes are increased in human glioma tissues with decreased SLC9A1 mRNA expression." (PMID 30333031, 2018). "Metagene scores of monocytes and macrophages (CGGA cohort) showed a positive correlation with increased SLC9A1 mRNA expression in the human glioma tissues." (PMID 30333031, 2018). "With GSEA, we detected differential immune phenotypes in gliomas with low or high SLC9A1 mRNA expression." (PMID 30333031, 2018). "Our study reveals that significantly higher SLC9A1 mRNA levels were detected in all grades of gliomas." (PMID 30333031, 2018). "In this study, we report a positive correlation between elevated NHE1 mRNA expression (SLC9A1) and shorter overall survival of glioma patients in the GSE16011 dataset." (PMID 30262908, 2018). "Gene set enrichment analysis (GSEA) further indicated that glioma with various SLC9A1 mRNA expression levels presented distinct status of angiogenesis." (PMID 30333031, 2018). "Elevated SLC9A1 mRNA levels in gliomas were correlated with reduced survival." (PMID 37298344, 2023). "In glioma cells, SLC22A18, SLC8A2, SLC9A1, and SLC34A2 were examined as the risk genes of glioma." (PMID 32565801, 2020). "High SLC9A1 levels of expression showed poor outcomes in each different grade gliomas." (PMID 30333031, 2018). "Worsened survival probabilities were correlated with the elevated SLC9A1 mRNA levels in gliomas." (PMID 30333031, 2018). "Furthermore, our univariate and multivariate cox analysis indicate SLC9A1 mRNA elevation as an independent factor for outcome of glioma patients." (PMID 30333031, 2018).
glioma (continued). "Taken together, these data strongly suggest that SLC9A1 (NHE1 protein) may serve as a new prognostic biomarker for gliomas." (PMID 30333031, 2018). "A study investigating the mRNA expression of SLC9A1 (NHE1) in CGGA and TCGA databases detected elevated mRNA levels of SLC9A1 among high-grade gliomas." (PMID 37298344, 2023). "Analysis of the RNAseq data revealed that SLC9A1 mRNA expression was higher in glioblastoma than WHO grade II and III gliomas in CGGA cohort as well as in TCGA cohort." (PMID 30333031, 2018). "To better understand the role of NHE1 in the progression of glioma, we compared the overall survival time of glioma patients between the group with high and low NHE1 (SLC9A1) mRNA expression in the GSE16011 cohort." (PMID 30262908, 2018). "In addition, increased SLC9A1 mRNA expression is negatively correlated with the infiltration of CD8 T cells (from both human and mouse glioma data)." (PMID 30333031, 2018).
melanoma (17 papers, 2011 to 2024). A malignant, usually aggressive tumor composed of atypical, neoplastic melanocytes. "The Na+/H+ exchanger NHE1 (SLC9A1) accumulates at the leading edge of migrating fibroblasts (human and hamster lung; murine embryonic), renal epithelial cells (canine), and melanoma cells (human MV3 and murine B16V cells)." (PMID 38214759, 2024).
Ataxia (12 papers, 2013 to 2025). Ataxia refers to impaired coordination of voluntary muscle movement. "A severe mutation in the human NHE1 gene SLC9A1 causes ataxia and deafness in a disease called Lichtenstein–Knorr syndrome." (PMID 32138345, 2020). "Further investigation into the prevalence of genetic mutations in the SLC9A1 gene appears to be called for, especially in the case of developmental disorders associated with ataxia and deafness that occur in Lichtenstein-Knorr syndrome." (PMID 25760855, 2015).
Stroke (12 papers, 2018 to 2025). Sudden impairment of blood flow to a part of the brain due to occlusion or rupture of an artery to the brain. "To explore underlying mechanisms, we conducted single cell RNA-seq transcriptome analysis in conditional Slc9a1 knockout (cKO) and wild-type (WT) mouse white matter tissues at 3 days post-stroke." (PMID 38509618, 2024).
gastric cancer (11 papers, 2019 to 2026). A primary or metastatic malignant neoplasm involving the stomach. "In gastric cancer, STAT3 has been found to translocate to the nucleus after activation and binds to promoter regions of target genes, including SLC9A1, which encodes NHE1." (PMID 41596231, 2026). "We identified a correlation between a bad survival prognosis in colon cancer patients and high expression levels of the SLC9A1 gene, similar to that found in gastric cancer patients." (PMID 36612049, 2022).
ischemic stroke (11 papers, 2019 to 2024). A stroke disorder caused by obstruction of blood flow to the brain, due to thrombotic (local blood clot formation) or embolic (due to a blood clot or other material traveling from another site) event. "Microglial Na/H exchanger-1 (NHE1) protein, encoded by Slc9a1, plays a role in white matter demyelination of ischemic stroke brains." (PMID 38509618, 2024).
colon carcinoma (10 papers, 2015 to 2023). "On the other hand, analysis via Kaplan–Meier curves indicates that those cases of colon cancer with high levels of SLC9A1 transcripts are correlated with worsened overall survival, but are without correlation with disease-free survival data." (PMID 36612049, 2022). "Here, we investigated the expression levels of four plasma membrane Na+/H+ exchanger isoforms (NHE1-4, encoded by SLC9A1-4 genes, respectively) in HCT116, HT29, SW480 and SW620 colon cancer cells." (PMID 36612049, 2022). "Results showed that cells from colon cancer tumors originating from the epithelium of the caecum and sigmoid are mainly enriched with SLC9A1 transcripts." (PMID 36612049, 2022). "We also investigated the expression levels of the SLC9A1 gene in colon cancer biopsies collected at the University Hospital of Tours (n = 136) and found a significant overexpression in tumors originating from the caecum, right and sigmoid colon in accordance with the single-cell RNAseq data." (PMID 36612049, 2022). "However, no significant change was found in SLC9A1 expression levels over the course of colon cancer progression." (PMID 36612049, 2022). "Finally, we assessed the 2D invasiveness of colon cancer cells under the pharmacological inhibition of NaV1.5 channels using TTX, of NHE exchangers using EIPA, in cells transfected with irrelevant small interfering RNA (siCTL), or targeted to SCN5A (siSCN5A) or SLC9A1 (siSLC9A1)." (PMID 36612049, 2022).
leukemia (10 papers, 2013 to 2025). A malignant (clonal) hematologic disorder, involving hematopoietic stem cells and characterized by the presence of primitive or atypical myeloid or lymphoid cells in the bone marrow and the blood. "Proximal region of SLC9A1 locus had a response to DNA damage uncovered by luciferase report assay in leukemia cell line K562." (PMID 35915613, 2022).